RNU1-38P (RNA, U1 small nuclear 38, pseudogene)
Gene: Small nuclear RNA gene on chromosome 2 (85,728,194 to 85,728,337, reverse strand). Ensembl gene ENSG00000199687.
Homologues: Orthologues: chimpanzee U1 (99% identical), macaque U1 (80% identical), mouse Gm25280 (52% identical). Paralogues in human: RNU1-1 (78% identical), RNU1-2 (78% identical), RNU1-27P (78% identical), RNU1-28P (78% identical), RNU1-3 (78% identical), RNU1-4 (78% identical), RNVU1-18 (78% identical), RNVU1-29 (78% identical), U1 (78% identical), RNU1-67P (77% identical), RNVU1-28 (77% identical), RNVU1-31 (77% identical), and 134 more.